IL10 (interleukin 10)
Diseases named in the same sentence as IL10 in open-access papers (continued):
Sharing a sentence is not in itself a finding about the gene and the disease.
viral infection (continued). "Similar expansions of IL-10-producing CD19+CD24hiCD38hi regulatory B cells in chronic HBV infections, and IL-10+ neonatal Bregs in Respiratory Syncytial virus (RSV), demonstrate that IL-10 production by Bregs limits adaptive responses to viral infections." (PMID 39346706, 2024). "IL-10 is widely recognized as a key inhibitor of adaptive T-cell responses and exhibits lung-protective activity during bacterial and viral infections." (PMID 38909235, 2024). "Studies have also shown that interferon-k3 participates in immune regulation during viral infection or autoimmune disorders, while IL-10 and IL-12 are closely related to the functions of T cells and NK cells." (PMID 38438842, 2024). "Regarding CD8+ T cells, IL-10 has been found to decrease their antigen sensitivity during chronic viral infections through specific signaling pathways." (PMID 39066368, 2024). "Nevertheless, IL-6 and IL-10 effects in the course of viral infections depend on its spatial and temporal delivery." (PMID 39457019, 2024). "An increase in WBC indicates a promotion in the cellular immune system response to control viral infection and as a result, an increase in the inflammatory cytokines expression such as IL-10 and CRP." (PMID 37396915, 2023). "Blackburn and Brooks suggested IL-10 is related to persistent viral infection; however, they neglected the role of TGF-β and IL-10 co-expressing TH3 cells." (PMID 36914565, 2023). "The mRNA levels of IL-1β, IL-6, and IL-8 showed a trend of decreases and then increases, while the mRNA levels of TNF-α and IL-10 significantly increased after viral infection." (PMID 36995259, 2023). "IL-10 plays an important role in tolerizing neonatal mice to viral infection as part of an important interplay of MMTV with commensal microbiota in the gut." (PMID 36869359, 2023). "B-1 cells act as the front line of defense against microbial or viral infections, by spontaneously secreting natural antibodies and cytokines, such as IL-10 and GM-CSF, and neutralizing pathogens before the launch of the adaptive immune response." (PMID 37109388, 2023). "THαβ CD4 T cells can secrete IL-10, and IL-10 can activate CD8 T cells and NK cells, causing immunity against virus infection." (PMID 36914565, 2023). "In the acute phase of viral infections, IL-10 released from innate immune cells and effector T cells balances immune damage and defence." (PMID 37629176, 2023). "In this study, we reconfirmed the critical role of IL-10 in viral infections using an IL-10 knockout RAW264.7 cell model and further confirmed the inhibitory effects of CVB4 replication and IL-10 expression by umifenovir." (PMID 36541788, 2023). "TH3 cells, which are detected in chronic virus infection, are characterized by co-secretion of IL-10 and TGF-β." (PMID 36914565, 2023). "Production of IL10 in CD8+ T cells is directly correlated with level of PRDM1 expression (Blimp-1) during acute viral infection." (PMID 37409113, 2023). "In contrast, IL-10 is an anti-inflammatory cytokine that has been demonstrated to regulate the immune response to viral infection by reducing the production of pro-inflammatory cytokines and limiting tissue damage caused by excessive inflammation." (PMID 37322049, 2023). "CD8+ T‐cells become significant producers of IL-10 during hypoxia and viral infection, in response to TCR activation, IL-21 stimulation or interaction with CD40 ligand on activated pDCs." (PMID 37359549, 2023). "It is worth noting that during chronic viral infections, NK cells can produce IL-10, which induces distinct phenotypic changes in DCs." (PMID 38022497, 2023). "Among these genes, the expression of the inflammatory downstream mediators IL-10, IL-1B, IL-6, and IL-8 was significantly reduced, an interesting finding that was rarely observed in viral infection." (PMID 37134013, 2023). "TGF-β can weaken the anti-viral effect of IL-10 and mildly control chronic virus infections to avoid fulminant viral diseases, such as viral hepatitis." (PMID 36914565, 2023).
viral infection (continued). "Given its fundamental immunoregulatory properties, IL-10 can equally promote the propagation or the shutdown of inflammatory responses and also direct the fate of parasite, bacterial and viral infections." (PMID 37359549, 2023). "Impaired T cell responses due to IL-10 secretion have been demonstrated in the context of various viral diseases, e.g., lymphocytic choriomeningitis, acquired immunodeficiency syndrome, hepatitis C, and Theiler’s murine encephalomyelitis." (PMID 37112814, 2023). "This in turn leads to the production of interleukin (IL)-10 knockout (IL-10−/−) to tolerize the host to viral infection." (PMID 36869359, 2023). "In contrast, anti-inflammatory macrophages protected lung cells from viral infection and diminished pulmonary inflammation by phagocytosis and production of anti-inflammatory factors related to IL-10 signaling pathway." (PMID 35440562, 2022). "Recent studies have found that there is a correlation between B cells and viral infections because B cells can secrete interleukin-10 (IL-10), IL-35 and transforming growth factor-β and play a negative immunomodulatory role." (PMID 35726529, 2022). "An in vitro study examining HCV infected human hepatocytes co-cultured with CD4+ T cells showed that the CD4+ T cells had increased expression of galectin-9, TGFβ and IL-10, indicating viral infection was driving regulatory phenotypes." (PMID 36032131, 2022). "During most acute viral infections, there is a cross-regulation for Th1 and Th2 activations primarily mediated by IL-10 and IFN-γ, respectively." (PMID 35437144, 2022). "The ratio of IL-12 to IL-10, for example, has been established as a predictive marker of clinical course in multiple sclerosis as well as disease severity in viral infections." (PMID 35261923, 2022). "Type I IFN signaling was reported to enhance IL-27 secretion by myeloid cell populations during MCMV and IAV viral infections, which in turn promoted IL-10 production by T cells in vivo." (PMID 35634328, 2022). "There is evidence to suggest that there is synergy between IL-10 and the PD-1/PD-L1 pathway during long-term viral infections." (PMID 36265003, 2022). "IL-10-producing Tregs play a role in balancing pathogen reduction and immunopathology in viral infections." (PMID 36016311, 2022). "The role of IL-10 in promoting Th2 response to antibody production occurring in viral infections is the first point." (PMID 35842705, 2022). "During viral infections, the exact role of IL-10 is also often unclear and depends on different factors such as, the virus type, the site of infection and the timing of the immune response." (PMID 35464430, 2022). "This aligns with the fact that during viral infections, the secretion of IL-10 has been found to inhibit the expression of major histocompatibility class II (MHC II) and co-stimulatory molecules CD80 and CD86 on APCs." (PMID 35572964, 2022). "IL-10 is known to be critical to protect the host from excessive tissue inflammation during acute viral infection." (PMID 35464430, 2022). "For bacterial and viral infections, the exact contribution of IL-10 is strongly dependent on different aspects such as pathogen type and infection site." (PMID 35464430, 2022). "HCMV-specific CD8+ T-cells are potent anti-viral effector cells in HCMV infected individuals, but evidence from other viral infections suggests that CD8+ T-cells can also produce the immunomodulatory cytokine IL-10." (PMID 36558866, 2022). "In particular, the expression of cytokines IL-1β, IL-6, and TNF-α was higher than that of the regulatory cytokine IL-10, resembling a cytokine profile characteristic of M1 phenotype, which typically intervene in counteracting bacterial and viral infections." (PMID 36016576, 2022). "We observed this increase in both B cells in CN2 and macrophages in CN8 after SIV infection, implicating elevated IL-10 expression in these cells as a host response to viral infection." (PMID 35447093, 2022).
viral infection (continued). "CD8+/CD25+ cells are induced by viral infection and some mechanisms dependent on IL-4 and IL-12, and they regulate Th1/Th2 reactions by production of IL-10 and IFNγ." (PMID 35337377, 2022). "The removal of IL-10 on a genetic level or blockade of its receptors or through anti-IL-10 antibodies leads to the elimination of viral infection or bacterial pathogen." (PMID 36298704, 2022). "While various innate and adaptive immune cell types have been identified as IL-10 producers, CD4+ and CD8+ T cells are important sources of IL-10 during viral infections." (PMID 35634328, 2022). "The role of IL-10–producing Breg cells has been further elucidated in mice models of acute and chronic viral infection." (PMID 34293057, 2021). "In our study, we used a heterogeneous group of spleen cells that, under viral infection and behavioural fever, decreased the inflammatory state by releasing Il10 and Tgfβ." (PMID 34445566, 2021). "During acute and chronic viral infections, it was observed that production of IL-10 by Bregs had both beneficial and detrimental effects in the pathogenesis of disease." (PMID 34293057, 2021). "The use of cultivatable murine norovirus (MNV) in mice has shown that mucosal inflammation of the intestine is induced by viral infection if the mice are unable to produce the anti-inflammatory interleukin 10 (IL-10) cytokine." (PMID 33441404, 2021). "Emerging data show that the regulatory cytokine IL-10 plays an essential role in promoting GC B cell responses during both experimental malaria and virus infections." (PMID 33529242, 2021). "This table shows currently described subsets of Bregs and IL-10–producing B cells during viral infections in humans and mice." (PMID 34293057, 2021). "It has been demonstrated that B cell–derived IL-10 can modulate the inflammatory responses during viral infections." (PMID 34293057, 2021). "Surprisingly, R848 and the combination of virus infection and R848 treatment primed GM-CSF MФ to express similar amounts of IL-10 and these levels reached comparable levels to those for LCMV-infected M-CSF cells stimulated with R848." (PMID 33331816, 2021). "Joller and colleagues demonstrated that TIGIT engagement can limit T cell–driven inflammation and protect against immune pathology via induction of immune-modulatory cytokine IL-10 in acute viral infection model." (PMID 33682797, 2021). "Emerging data show that the anti-inflammatory cytokine Interleukin (IL)-10 can function to sustain an already established humoral immune response during acute and chronic virus infections." (PMID 33529242, 2021). "The IL10RB and IFNAR2 share an inverse relationship for viral infection, wherein macrophages have been reported to secrete higher IL10 in comparison to IFNAR246." (PMID 34315903, 2021). "IL-10 is related to T cell dysfunction during persistent viral infection, and blocking receptors of IL-10 with neutralizing antibodies subside persistent infection symptoms and enhance the secretion of IFN-γ of virus-specific CD8+ T cells." (PMID 33728333, 2021). "For instance, virus infections have been shown to modulate the host immune responses by secretion of orthologues to human cytokines like IL-10, which would lead to a distinct increase in peripheral p70S6k phosphorylation." (PMID 33800846, 2021). "One subject, who was found to have had a concurrent systemic viral infection, had an increase in IL-1β, IL-6, IL-10, and TNF-α following chDAB4 incubation which appeared to be inversely proportion to chDAB4 concentration used." (PMID 34231102, 2021). "In fact, herpesviruses have evolved multiple strategies to promote the production of IL-10, which, by dampening beneficial to the host T cell–mediated immunity, facilitates the establishment of persistent virus infections." (PMID 34293057, 2021).
viral infection (continued). "During the early stage of viral infection, cytokines (IL-1, IL-2, IL-8, IL-10, CCL2, CCL7, IFN-α, IFN-β, and TNF-α) have essential functions in the recruitment of immune cells, defense against the infection, and promotion of inflammation." (PMID 34603560, 2021). "IL-10 shows a prominent role in the immune response by suppressing the viral disease via activation of NK cells and by triggering immunoregulatory and anti-inflammatory cytokines against the antigen by associating with mast cells, B cells, and certain T cells." (PMID 33557110, 2021). "Distinct from reports of virus infection, we found that IL-10 was expressed by conventional, Foxp3-negative effector CD4 T cells and functioned in a B cell-intrinsic manner only during the first 96 hours of Plasmodium infection to support humoral immunity." (PMID 33529242, 2021). "Infection with other viruses infection, such as Japanese encephalitis virus and Zika virus, has also been shown to result in a decrease in IL-10 expression, but the exactly mechanism underlying GNAstrV infection needs further study." (PMID 33647718, 2021). "In summary, this study highlights that WAT and in particular GWAT depots are an abundant source of IL-10 and IL-21 in the context of a viral infection." (PMID 32455939, 2020). "Different studies have reported that in the course of porcine viral infections, virus-induced Tregs produce IL-10 and TGF-β, a mechanism that allows viruses to persist in the host by controlling the intensity of IFN-γ production and cytotoxic activity." (PMID 32376618, 2020). "In summary, these data reveal an important role of the TIGIT pathway in limiting immune-mediated tissue damage during acute virus infection in an IL-10-dependent manner." (PMID 32152316, 2020). "IL-10 is a critical protective modulator which can attenuate the activation of lymphocytes and inflammatory cascades during virus infection." (PMID 33349263, 2020). "Macrophages produce cytokines such as interferons and IL-10 upon viral infection to modulate anti-viral immune responses." (PMID 32849638, 2020). "During the resolution of viral infections and inflammation, T reg cells tower over other cell types in IL-10 secretion." (PMID 33066100, 2020). "Th2, which controls humoral immunity, is effective for protection against most bacterial and several viral infections and is characterized by the formation of cytokines IL-4 and IL-10 and enhanced production of IgG1." (PMID 32168741, 2020). "TNF-α is a key factor for viral crossing of the BBB, and IL-10 was also proved to facilitate viral infection." (PMID 33597934, 2020). "Viral infection increased the released of pro-tumorigenic cytokines including the immune suppressive IL-10 and VEGF and the pro-inflammatory cytokines IL-6 and IL-8." (PMID 32418990, 2020). "Cytokines including GM-CSF, IL-2, IL-1β, TNF-α, IFN-γ, and IL-10 are key molecules that regulate innate and adaptive immune responses to viral infection." (PMID 31412594, 2019). "In viral infections, the IL-10 produced by Treg cells is closely related to the maintenance of the immunopathological balance." (PMID 30760822, 2019). "Our findings strongly indicate that IAV coinfection compromises the host’s ability to control Mtb infection via the production of IL-10, which was rapidly induced upon viral infection." (PMID 30998505, 2019). "In this study, we have demonstrated that NK cells are a key source of IL-10 during the early phases of MCMV infection and that NK cell-derived IL-10 is important to protect the host against liver damage during a persistent virus infection." (PMID 31803193, 2019). "To overcome the limitation, using the Cre induced recombination of Il10 genomic locus, we generated NKp46-Cre-Il10fl/fl mice to elucidate the regulatory role of NK cells during viral infection." (PMID 31803193, 2019). "Previous studies have proven that IL-10 contributes to the development of immunosuppression in some virus infection hosts." (PMID 31835539, 2019).
viral infection (continued). "Regarding viral infection, IL-10-producing B cells were reported to inhibit hepatitis B virus (HBV)-specific CD8+ T cell responses, and the frequency of IL-10- producing B cells was found to be correlated with HBV pathogenesis." (PMID 31474988, 2019). "During viral infections, some viruses also exploit the benefits of IL-10 for hijacking the immune response." (PMID 30581370, 2018). "Collectively, our scRNA-seq analyses highlight that IL-10-producing CD4 T cells responding to chronic viral infection are comprised of multiple transcriptionally distinct subsets." (PMID 30487586, 2018). "Collectively, these data demonstrate that Tfh-produced IL-10 is essential for maintaining protective humoral responses during chronic viral infection." (PMID 30487586, 2018). "IL‐10 is an example of the multifaceted role a single cytokine can have on viral infection and the UPR." (PMID 29632667, 2018). "We also observed strongly increased levels of IL-10 in liver tissue and plasma in response to viral infection." (PMID 29953538, 2018). "Collectively, these data demonstrate that the expansion and accumulation of IL-10+ Tfh cells critically relies on inflammatory and antigenic signals propagated during the early phase of chronic viral infection." (PMID 30487586, 2018). "In humans, high levels of IL-10 production in response to some viral infections plays a role in viral persistence, by suppressing immune functions." (PMID 30500849, 2018). "IL-10 is involved in the impairment of T cell function during persistent viral infections, and blockage of the IL-10 pathway alone is sufficient to restore T cell activities and increase viral control." (PMID 29439673, 2018). "To investigate the transcriptional heterogeneity of IL-10-producing CD4 T cells responding to chronic viral infection, we performed scRNA-seq on IL-10-expressing CD4 T cells from mice infected with persistent LCMV Cl13." (PMID 30487586, 2018). "Taken together, these results demonstrate that Tfh cells responding to chronic viral infection exhibit an enhanced and sustained capacity to coordinately produce both IL-10 and IL-21." (PMID 30487586, 2018). "NK cells are an important source of TGF-β and a main early producer of IL-10 in response to viral infection." (PMID 29439673, 2018). "In the bacterial exposure (SR) and viral infection (Flu) models, we observed an increased proportion of IL-10+ LAG3+CD49b+ T cells that are CD8+, which is the predominant population in the Flu model." (PMID 30510554, 2018). "Several studies have described CD4+ or CD8+ T cells as the critical source of IL-10 during protozoan and viral infection, contributing either to protection or to chronicity." (PMID 28584007, 2017). "Studies using lymphocytic choriomeningitis virus (LCMV) infections with strains that provoke either acute or persistent infections have helped understand the role of IL-10 in viral infections." (PMID 28316998, 2017). "It thus appears that antiviral and inflammatory signals elicited during viral infections trigger activated T cells to produce IL-10 as a feedback regulatory mechanism that limits excessive inflammation." (PMID 28316998, 2017). "During MMTV infection via oral routes, LPS on MMTV virions promotes interlukin-6 (IL-6) secretion following virus infection of gut dendritic cells or macrophages, which in turn stimulate B cells that secrete IL-10." (PMID 29211815, 2017). "IL-10 down-regulates the immune response after virus infection by inhibiting IFN-γ production, antigen presentation, and macrophage production of IL-1, IL-6, and TNF-α." (PMID 28086978, 2017). "IL‐10 promotes T cell exhaustion, and IL‐10 blockade reverses T cell dysfunction during chronic viral infections." (PMID 28545567, 2017). "In various infectious, diseases such as leishmaniasis, trypanosomiasis and viral infection, are concordance with IL-4 as well as IL-10 production (as Th2 cytokines) and L-Arg increased catabolism in M2 macrophages." (PMID 29253854, 2017).